CDK2 (cyclin dependent kinase 2)
Diseases named in the same sentence as CDK2 in open-access papers (continued):
Sharing a sentence is not in itself a finding about the gene and the disease.
neuroblastoma (continued). "The decrease in PCLAF gene expression significantly downregulated CyclinA2, CyclinB1, CyclinD1, CyclinE2, CDK2, and CDK6, which further showed that downregulation of PCLAF can inhibit the proliferation of neuroblastoma." (PMID 35210406, 2022). "AT7519, a CDK2 inhibitor (70.0% cytotoxicity), has shown excellent preclinical anti-tumor responses against MYCN-amplified neuroblastoma, and is currently in phase II clinical trials for adults (NCT00390117) and children (NCT01627054)." (PMID 34722256, 2021). "Used at low concentrations, Dinaciclib is a broad CDK inhibitor (CDK1, 2, 5, and 9), but its antagonistic effect on CDK2 and CDK9 has been attributed to its ability to suppress neuroblastoma cell proliferation." (PMID 33796454, 2021). "Here, we show that CYC065 (fadraciclib), a clinical inhibitor of CDK9 and CDK2, selectively targeted MYCN-amplified neuroblastoma via multiple mechanisms." (PMID 33016930, 2020). "In 2011, EAs’ group reported that miR-885-5p targeted cyclin-dependent kinase 2 (CDK2) and inhibited proliferation and survival of neuroblastoma." (PMID 29088865, 2017). "Chelators of the AHC class can regulate the expression of various proteins involved in cell-cycle control such as CDK2, cyclins A, B1, D1, D2, D3, WAF1 (inhibitor of CDKs) as shown for HNI/311 in neuroblastoma and an erythroleukemia cell line." (PMID 20184758, 2010). "We show that CBN profoundly inhibits neuroblastoma cell proliferation, angiogenesis, and invasion in a dose-dependent manner, and induces cell cycle arrest through the inhibition of the AKT pathway and downregulation of miR-34a’s targets CDK2 and E2F1." (PMID 35454815, 2022). "However, the prognostic effects of CCNE1, CDK2, CHEK2 and SESN1 were different in paediatric neuroblastoma." (PMID 35655142, 2022). "Next we attempted to determine whether CDK2 and CDK9 inhibition, when combined with IGF2BP1 inhibition, would have an additive effect on neuroblastoma cell replication." (PMID 33796454, 2021). "Knockdown of CDK2 or treatment with the CDK2 inhibitor roscovitine induces apoptosis in MYCN-amplified neuroblastoma cell lines but not in those with MYCN single copy." (PMID 33628735, 2020). "Interestingly, suppression of CDK2 activity is required for reduced proliferation and survival of the primary neural crest derived tumour and its inhibition was demonstrated to be synthetic lethal in MYCN overexpressing neuroblastoma." (PMID 25594028, 2014). "The mRNA expression levels of CCNE1, CDK2, CHEK2 and SESN1 in paediatric neuroblastoma patients with or without MYCN amplification were also investigated." (PMID 35655142, 2022). "We show that treatment of mouse neuroblastoma Neuro-2A cells with Tet34, but not its scrambled control (Tet34s), induced cell proliferation, as manifested by changes in protein levels of transcription factors and progrowth molecules cyclin D1, PCNA, Sox5, and Cdk2." (PMID 36162508, 2022).
liver cancer (36 papers, 2002 to 2025). An epithelial or non-epithelial malignant neoplasm that arises from the liver. "Recent studies have begun to understand the precise role of E-type cyclins and their associated kinase CDK2 for the development of liver cancer." (PMID 34830835, 2021). "Ccne1 overexpression cause liver tumor development in mice, Cdk2 plays a key role in cell cycle progression in hepatocyte, and cyclin-dependent kinase 1 (Cdk1) is essential for cell division of liver cancer." (PMID 32570707, 2020). "LINC00630 increases E2F1 binding to the CDK2 promoter region, stimulates CDK2 transcription, and thereby accelerates the malignant development of liver cancer." (PMID 37240281, 2023). "The present study is the first to demonstrate the inhibitory effects of buforin IIb on CDK2 and cyclin A, which unveils the molecular basis by which buforin IIb affects the cell progression of liver cancer cells." (PMID 31231581, 2019). "In this study, bioinformatic analysis found that SKA3 has an important relationship with CDK2, and after knocking down SKA3, CDK2 was the major downregulated protein, which explained the G2 arrest of liver cancer cells after knocking down SKA." (PMID 31804459, 2019). "H2A.Z.1 depletion selectively suppressed positive G1/S cell cycle components, such as CDK4, CDK6, cyclinD1 and CDK2, and simultaneously induced the expression of potent negative cell cycle regulators, p21WAF1/Cip1 and p27Kip1, in liver cancer cells." (PMID 26863632, 2016). "Our results showed inhibition of DNA methylation by either 5-aza-dC treatment or knockdown of DNMT1 caused the induction of miR-31 expression, and consequently suppressed HDAC2 and CDK2 expression in liver cancer cells." (PMID 25797269, 2015). "Our results showed that ectopic expression of miR-31 resulted in suppression of HDAC2 and CDK2 protein expression in liver cancer cells." (PMID 25797269, 2015). "Taken together, we present evidences that miR-31 functions as a tumor suppressive miRNA by directly regulating HDAC2 and CDK2 expression in liver cancer progression." (PMID 25797269, 2015). "Precious studies have suggested that FOXM1 overexpression was associated with tumor progression in patients with clear cell renal cell carcinoma, and FOXM1 silence could lead to liver cancer cell growth and a decline of CDK2 expression." (PMID 38342795, 2024). "Thus, by inhibiting VEGFR2/CDK-2, compound 6b has the potential to be a powerful drug against liver cancer." (PMID 39449145, 2024). "CBG could reduce the expression of EGFR and CDK2 activity in human liver cancer cells, thereby inhibiting the growth of tumor cells, and enhancing the inhibitory effect of CBG on the proliferation potential of human liver cancer cells." (PMID 35011278, 2021). "In contrast, the expression of Cyclin-dependent kinase 2 is dispensable for the progression of liver cancer in mice and lacked diagnostic or prognostic value in patients." (PMID 34830835, 2021). "Therefore, buforin IIb suppress cell cycle by regulation CDK2 and cyclin A expression in the liver cancer." (PMID 31231581, 2019). "Notably we also found that treatment of DZNep elicited remarkable suppression of EZH2, HDAC2 and CDK2 proteins with concomitant increase of miR-31 expression in liver cancer cells." (PMID 25797269, 2015). "Finally, we aimed to analyse whether our findings regarding CCNE1 and CDK2 in murine liver cancer can also basically be found in HCC patients." (PMID 34830835, 2021).
liver cancer (continued). "Ultimately, the interaction between RFC and PCNA or between CDK2 and CyclinE, the telomerase activity and the microsatellite instability (MSI) are significantly increased in the liver cancer stem cells." (PMID 27782152, 2016). "Our results indicate HOTAIR causes microsatellite instability (MSI) and abnormral expression of cell cycle related gene, e.g. CDK2, CyclinE, CDK4, CyclinD1, PCNA, ppRB, E2F1 in liver cancer stem cells." (PMID 26172293, 2015). "Together, these results suggest that CCNE1 is involved in dedifferentiation and acquisition of invasive features of liver cancer cells independent of CDK2." (PMID 34830835, 2021). "CCNA2 gene was first detected in primary liver cancer cells, which appeared in the late G1 and could bind to CDK and CDK2, Respectively; it could affect the G1/ S phase and G2/M phase of the cells." (PMID 31956366, 2020). "Flavopiridol is an inhibitor of cyclin-dependent kinases (CDKs) (including CDK1, CDK2, CDK4, CDK5, CDK6, CDK7, CDK8, and CDK9) and has been investigated for the treatment of several types of cancers, including leukemia, liver cancer, and renal cancer, in clinical phase 2 trials (24, –, 26)." (PMID 31822599, 2019). "Therefore, HULC increases the cellular autophagy by increasing LC3II dependent on Sirt1.Noteworthy, excessive HULC reduces the expression of PTEN, β-catenin and enhances the expression of SAPK/JUNK, PKM2, CDK2, NOTCH1, C-Jun in liver cancer cells." (PMID 29895332, 2018). "Our results showed that p21WAF1/CIP1 inhibited [3H]thymidine incorporation and reduced cdk2 kinase activity in human liver cancer cells but did not affect expression of cdk2 and cdk4." (PMID 11870547, 2002).
leukemia (33 papers, 2012 to 2025). A malignant (clonal) hematologic disorder, involving hematopoietic stem cells and characterized by the presence of primitive or atypical myeloid or lymphoid cells in the bone marrow and the blood. "In leukemia, cordycepin also causes S-phase cell cycle arrest by suppressing the expression of cyclin A2, cyclin E, and cyclin-dependent kinase 2 (CDK2)." (PMID 39858295, 2024). "It was found that our combination downregulated p27, cyclin D3 and CDK2, which agrees with previous reports showing that the decrease in Hsp90 is associated with the G1 arrest in leukemia cells." (PMID 32397330, 2020). "Propolis caused cell cycle arrest by upregulating p21 and p27 gene expression and downregulating the expression of cyclin A, cyclin B, and CDK2 in leukemia cells." (PMID 41438200, 2025). "This experiment demonstrated that HHT treatment inhibited the leukemia development in THP1 CDK2-wt xenograft mice but had limited effect on THP1 CDK2-3As/T160E xenograft." (PMID 35595767, 2022). "In this study, we showed that it can induce the autophagic degradation of CDK2 and suppress leukemia development." (PMID 35595767, 2022). "Further, we demonstrate that HHT induces autophagic degradation of the CDK2 protein via tripartite motif 21 (Trim21) in cancer cells, which is confirmed in a leukemia mouse model and in human primary leukemia cells." (PMID 35595767, 2022). "The analysis indicates that CDK2 expression level is positively correlated with leukemia development." (PMID 35595767, 2022). "To further determine the role of CDK2 in leukemia cells, we used a CRISPR-Cas9 approach to establish a CDK2 deficient, THP1 cell line (THP1 CDK2−/−)." (PMID 35595767, 2022). "To further assess the relationship between treatment with HHT and the CDK2 protein levels, we probed for a significant correlation between the two primary leukemia cells taken from 6 AML patients." (PMID 35595767, 2022). "For example, clinical trials of the flavonoid-derived inhibitor of cyclin-dependent kinase 2 (CDK2) flavopiridol have demonstrated its strong therapeutic potential to treat several forms of leukaemia." (PMID 34684801, 2021). "For example, 17p loss increases resistance to seven different drugs in leukaemia (LAML) and five of these target cell cycle/mitotic regulators (KIF11, CDK2/7/9, WEE1, PLK1, microtubules)." (PMID 31974379, 2020). "The authors proposed a pathway for DHA-mediated cell cycle arrest in S-phase in leukemia cells: initiation of p21 activation, which in turn leads to inhibition of the CDK2/Cyclin A complex, hypophosphorylation of pRb and subsequent S-phase arrest." (PMID 28817068, 2017). "Consistent with its role as a tumor suppressor, CRIF1 interacts with and inhibits CDK2 to induce cell cycle arrest in leukemia cells." (PMID 25997448, 2015). "Our experiments here demonstrated that HHT could inhibited leukemia proliferation in vitro and in vivo by inducing the degradation of CDK2 protein." (PMID 35595767, 2022). "It triggered us to study the role of CDK2 in HHT treatment for leukemia." (PMID 35595767, 2022). "To determine whether HHT achieves its therapeutic efficacy when it targets the CDK2 protein, we tested the compound in one mouse model of leukemia involving bone marrow (BM) transplantation (BMT)." (PMID 35595767, 2022). "Altogether, the ability of HHT to effectively inhibit the development of leukemia in a mouse model may be relevant to the degradation of CDK2 protein." (PMID 35595767, 2022). "As expected, treatment with HHT strongly decreased levels of CDK2 protein in leukemia mice." (PMID 35595767, 2022). "Further work is required to identify the precise mechanism(s) by which CDK2 inhibition mediates the preservation and the increase of pathogen-specific and leukemia-specific effectors, while suppressing activation and expansion of alloreactive effectors, as well as to confirm these results in vivo." (PMID 30863749, 2019).
leukemia (continued). "Cyclin E controls entry from late G1 to S phase and this is followed, as DNA synthesis begins, by an increase in Cyclin A and associated CDK2 Cyclin A. CDK2 protein expression was found to be lower in metastatic MHCC97L liver cells and leukemia cells treated with DHA." (PMID 28817068, 2017). "In this study, co-immunoprecipitation results showed that CRIF1 only interacted with CDK2, and suggested CRIF1 may act as CKI when combined with CDK2, and prevent cell cycle progression of leukemia cells." (PMID 24520316, 2014). "CRIF1 may play a regulatory role in the BM microenvironment-induced leukemia cell cycle arrest possibly through interacting with CDK2 and acting as a cyclin-dependent kinase inhibitor." (PMID 24520316, 2014). "Moreover, HHT enhances the binding affinity between CDK2 and tripartite motif 21 (Trim21) by specifically targeting the interaction between CDK2 and Cyclin A. This leads to the autophagic degradation of CDK2, thereby modulating the cell cycle of leukemia cells." (PMID 39949739, 2025). "Treatment alternatives for cases of leukemia with CDKN2A mutations encompass the targeting of the CDK2-SKP2 axis, the utilization of the small-molecule CDK4/6 inhibitor known as palbociclib, and the application of the innovative CDK2/9 inhibitor referred to as fadraciclib." (PMID 39443269, 2024). "A subpanel of leukemia was selectively inhibited by compound 5l, which has nanomolar IC50 values for FLT3 (IC50 = 36.21 ± 1.07 nM), and CDK2 (IC50 = 8.17 ± 0.32 nM)." (PMID 38794229, 2024). "Compared with parental sensitive leukemia cells, the protein expression levels of CDK2, CDK4, Cyclin D1 and Cyclin E in chemo-resistant leukemia cells were relatively elevated." (PMID 37814227, 2023). "Our present study proved that the expression levels of CDK2, CDK4, Cyclin D1 and Cyclin E were more abundant in the chemo-resistant leukemia cells than in their parental cells." (PMID 37814227, 2023). "Comparing with their parental sensitive leukemia cells, the protein expression levels of CDK2, CDK4, Cyclin E and Cyclin D1 relatively elevated in chemo-resistant leukemia cells." (PMID 37814227, 2023). "These experiments suggest that CDK2 protein is critical for leukemia cell proliferation and HHT inhibited AML cell proliferation by targeting CDK2." (PMID 35595767, 2022). "Both this set of primary leukemia cells and cells from a healthy donor were treated either with HHT or vehicle control; we then measured levels of CDK2." (PMID 35595767, 2022). "Meanwhile, ampelopsin did not result in a significant reduction in the expression of CDK proteins, including CDK4, CDK2, and CDK1, in both leukemia cell lines." (PMID 33924032, 2021). "In limited studies, stilbenes were proved to be highly related to targets of leukemia treatments, for example, pterostilbene, a 3′, 5′-dimethoxy-resveratrol interacted with 25 targets, including MAPK14, CDK2, and HSP90AA1, which are highly related to leukemia." (PMID 32104190, 2020). "In human leukemia cells, inhibitors of ERK have been reported to increase the phosphorylation of cdc25c expression at the G2/M arrest stages and decrease p21 and CDK2 expression at the endoreduplication stages." (PMID 24137330, 2013). "Thus, THP1 leukemia cells were treated with HHT, and within 3 hours the treatment disrupted interactions between CDK2 and its major partners – Cyclin A and Cyclin E." (PMID 35595767, 2022). "Also known as alvociclib, this wide spectrum CDK inhibitor targets CDK1, CDK2, CDK4, CDK6, CDK7 and CDK9 and displays antiproliferative efficacy in several solid tumours and sarcomas, as well as in leukaemia, lymphoma and multiple myeloma." (PMID 25625291, 2015).
leukemia (continued). "In addition, recent studies demonstrated that Roscovitine (a potent small molecule inhibitor of CDK2, and weak inhibitor of CDK1, 5, 7, and 9) treatment inhibits the function of the alloreactive T cells while allowing preservation of leukemia-specific and pathogen-specific effectors." (PMID 30863749, 2019).